TF (transferrin)
Diseases named in the same sentence as TF in open-access papers (continued):
Sharing a sentence is not in itself a finding about the gene and the disease.
COVID-19 (81 papers, 2020 to 2025). A disease caused by infection with severe acute respiratory syndrome coronavirus 2. "Platelet-monocyte interaction in COVID-19 was strongly associated with monocyte TF expression and global coagulation activation as shown by elevated fibrinogen and D-dimers." (PMID 37255704, 2023). "Recently, a panel of five proteins with downregulated expression, namely, albumin (ALB), apolipoprotein A1 (APOA1), apolipoprotein C1 (APOC1), gelsolin (GSN), and transferrin (TF), was identified as a core signature associated with the severity of COVID-19." (PMID 34471261, 2021). "Regarding the association between COVID-19 and bad prognosis, biomarkers, such as transferrin, ferritin, and D-dimer, were observed, and serum levels of ferritin correlated positively with age (rs = 0.34) and height (rs = 0.41)." (PMID 34071293, 2021). "Biomarkers of iron metabolism (i.e., ferritin, transferrin (TF), lactoferrin (LF), etc.)and Hb could provide risk stratification strategies for COVID-19 management." (PMID 38555403, 2024). "Other biomarkers of iron metabolism (i.e., ferritin, TF, LF, etc.)and Hb could provide risk stratification strategies for COVID-19 management, as initial anemia is strongly linked to increased CFR." (PMID 38555403, 2024). "Therefore, transferrin/antithrombin ratio showed increment with age and was higher in males, which corelated with the risk for severe COVID-19, the risk being higher in males and increases with age." (PMID 35849261, 2023). "Upregulation of TF expression has been associated with thrombus formation in COVID-19 lungs, while post-mortem specimens have demonstrated upregulated TF expression in the lung of fatal COVID-19 cases with loss of thrombomodulin, implying a shift towards a prothrombotic state." (PMID 37175942, 2023). "A possible role for TF in the thrombosis associated with severe COVID-19 has been proposed." (PMID 35409421, 2022). "In addition, oxidative stress promotes TF expression to initiate coagulation, and a hypercoagulable state, associated with thrombosis in patients with severe COVID-19, may be a marker of ferroptosis." (PMID 37303950, 2023). "Thus, low levels of transferrin can pose a risk for mortality in hospitalized COVID-19 patients." (PMID 35849261, 2023). "Thus, transferrin may play a role in coagulation in patients with severe COVID-19 because the severe form of this disease has been linked with disseminated intravascular coagulation and thrombosis." (PMID 35849261, 2023). "Clinically, it has been found that a ferritin/TF ratio > 10 is associated with a 5-fold increased risk of ICU admission and an 8-fold increased risk of mechanical ventilation in COVID-19 patients." (PMID 40566632, 2025). "In the context of COVID-19, elevated TF expression in monocytes has been reported in severe cases, suggesting that viral infections can broadly activate coagulation pathways via innate immune mechanisms." (PMID 41012652, 2025). "We observed lower levels of ALB, APOM, and TF in patients with COVID-19 (and more so in patients with COVID-19 who were admitted to the ICU) relative to patients without COVID-19." (PMID 39027641, 2024). "In our cohort, higher ferritin levels, and lower levels of iron and transferrin saturation were also observed in post-COVID-19 patients compared to healthy controls." (PMID 38324145, 2024). "NETs contribute to coagulation and inflammation in COVID-19 patients by increasing TF expression and platelet aggregation." (PMID 39459851, 2024). "At baseline, iron and transferrin concentrations were significantly lower in the COVID-19 patients compared with the controls (p < 0.001 for both)." (PMID 38337670, 2024). "Serum TF levels decrease within the 1st week of hospitalization in many COVID-19 patients; however, a continuous decline is prominent among subjects with fatal outcomes." (PMID 38555403, 2024).
COVID-19 (continued). "A ferritin/TF ratio >10 predicts a five-fold higher risk of ICU admission and an eight-fold higher risk for need of mechanical ventilation in COVID-19 patients." (PMID 38555403, 2024). "As expected, the total concentration of transferrin diminished in patients with COVID-19 at the onset of the treatment (Sample 1) and remained reduced after treatment (sample 2)." (PMID 38673719, 2024). "We found altered glycopeptide abundances among proteins important in COVID-19, including haptoglobin, transferrin and immunoglobulin A (IgA)." (PMID 37474612, 2024). "Transferrin is an acute phase reactant, and the acute phase reactions are of great importance in the diagnosis and treatment of COVID-19." (PMID 38673719, 2024). "An additional premise regarding the importance of 5-sialoTRF is the dependence of its concentration on the severity of the disease, which can promote this transferrin fraction as a prognostic marker of COVID-19 patients’ survival." (PMID 38673719, 2024). "Iron (II,III) levels (87.3 ± 30.9 vs. 72.8 ± 28.2, P < 0.05) and transferrin saturation (25.1 ± 9.52 vs. 20.6 ± 7.81, P < 0.05) were significantly decreased 3-months post-COVID-19 patients compared to healthy controls." (PMID 38324145, 2024). "The differences in the transferrin isoforms in COVID-19 patients compared to other diseases can be used diagnostically." (PMID 38673719, 2024). "In severe COVID-19, platelet activation and TF expression by monocytes leading to platelet-monocyte interaction are associated with COVID-19 severity and mortality." (PMID 36830874, 2023). "At 6 days post infection, Ifnb1 expression was significantly attenuated by 4-OI, providing further indication that suppressing type I IFN signaling is critical in reducing TF-mediated coagulopathy in COVID-19." (PMID 37316487, 2023). "Such a decline in transferrin levels has been observed in severe COVID-19 compared with mild disease." (PMID 35849261, 2023). "This occurred despite low levels of serum iron, which implied that COVID-19-induced inflammation exerted dominance over transferrin-inducing mechanisms and prevented its elevation under low iron conditions." (PMID 35849261, 2023). "Other factors, such as ratio of lymphocytes, direct and total bilirubin, albumin, transferrin, pH, protein in the pleural fluid, and SpO2, showed very low RR values (0.17 to 0.48), which fits with their inverse correlation with COVID-19 severity." (PMID 36668902, 2023). "COVID-19 patients with severe disease showed significantly lower mean transferrin values than those with mild disease." (PMID 35849261, 2023). "We built regulatory networks with miRNA- and TF-genes to learn more about the transcriptional and posttranscriptional mechanisms that control the genes that are shared by MG and COVID-19 patients." (PMID 38384322, 2023). "Along similar lines, in hospitalized COVID-19 patients, within the first week of hospitalization, transferrin levels were found to decrease in all patients." (PMID 35849261, 2023). "After infection with COVID-19, the increase in TF composition was statistically significant (P-value=0.001)." (PMID 36843827, 2023). "In a COVID-19-related study, transferrin levels were low at the time of hospitalization and a decrease in transferrin levels persisted more strongly in patients with high oxygen demand over the time of hospitalization (examined up to 6 days)." (PMID 35849261, 2023). "An increased level of ferritin and transferrin was found in COVID-19 patients and SARS-CoV-2-infected cells as well, suggesting the involvement of these iron metabolism-related proteins in the development of the disease." (PMID 35682873, 2022). "While the inflammatory marker and iron-storage protein ferritin was strongly increased, the plasma iron and transferrin levels were decreased in COVID-19 patients." (PMID 35181867, 2022). "As mentioned in this paper, TF-positive EVs are abundantly expressed in the circulation of COVID-19-infected patients." (PMID 36441349, 2022).
COVID-19 (continued). "The TF-miRNA coregulatory network of the seven overlapping gene targets of vitamin D against COVID-19/HCC was analyzed using NetworkAnalyst." (PMID 36275701, 2022). "Considering that the expression of transferrin and the risk of severe cases in male patients were higher than those in female patients and increased with age, this relationship could explain the higher infection rate and mortality in elderly male COVID-19 patients." (PMID 35813823, 2022). "Transferrin may be involved in COVID-19-related IDA, hypercoagulopathy, and ischemic stroke." (PMID 35682873, 2022). "This was also evident for acetone, Fischer’s ratio, H4A1, H4CH, H4FC, H4PL, L3CH, creatinine and transferrin saturation in the analysis of hospitalized males against male COVID-19 patients who stayed in an outpatient setting." (PMID 36557315, 2022). "Although 78.9% of COVID-19 patients (N = 105) were undergoing LMWH treatment, when thrombin generation was triggered either by TF or silica, COVID-19 patients had similar lag-time and ETP but higher peak than healthy controls." (PMID 33833254, 2021). "In COVID-19 patients higher LDH, CRP, IL-6, and D-dimer values were associated with longer lag-time triggered by TF." (PMID 33833254, 2021). "In the present work, an analysis of the status of D-dimer, transferrin, and ferritin was performed, which are some of the most commonly used inflammatory markers for monitoring COVID-19 patients." (PMID 34071293, 2021). "We enrolled adult patients hospitalized with a clinical diagnosis of COVID-19 and measured serum iron, transferrin saturation, ferritin, hepcidin and serum catalytic iron daily." (PMID 34608227, 2021). "This two-center observational study of 136 adult hospitalized COVID-19 patients analyzed the association between disease severity and initial serum iron, total iron-binding capacity (TIBC), and transferrin saturation (TSAT) levels." (PMID 34183735, 2021). "Their experiments suggest bi-directional signaling between platelets and monocyte TF expression leading to activated inflammation and hypercoagulability in COVID-19." (PMID 33378321, 2021). "Our data consolidate low serum iron, low transferrin, and high IL-6 as important predictors of disease severity in COVID-19." (PMID 34960751, 2021). "Ex vivo studies revealed that platelets isolated from COVID-19 patients were able to induce TF expression by monocytes." (PMID 33378321, 2021). "In conclusion, the role of transferrin in the course of COVID-19 disease and in particular of COVID-19-related coagulopathy should be considered and further examined in ongoing clinico-pathological investigations." (PMID 32751741, 2020). "If the role of transferrin is confirmed in the pathogenesis of severe COVID-19 disease and in COVID-19-related coagulopathy, it is a candidate diagnostic marker for the monitoring of COVID-19 progression and may guide the use of anticoagulants in COVID-19 patients." (PMID 32751741, 2020). "Of interest, anticoagulant treatment has been reported to be effective in a subset of severe COVID-19 patients, and researchers have determined that the pro-coagulant transferrin is upregulated in SARS-CoV-2 infections." (PMID 33066821, 2020). "By applying OxoScan-MS to quantify 1,002 glycopeptide features in the plasma glycoproteomes from patients with COVID-19 and healthy controls, we found that severe COVID-19 induces differential glycosylation in IgA, haptoglobin, transferrin and other disease-relevant plasma glycoproteins." (PMID 37474612, 2024). "Besides, those COVID-19 patients with significantly lower serum iron concentrations and transferrin levels are commonly anemic, indicating a potential inverse relationship between serum iron levels and the severity of COVID-19." (PMID 37303950, 2023).
COVID-19 (continued). "Ferritin can sequester a large number of iron ions, and the higher affinity of iron to ferritin and lactoferrin than transferrin (although transferrin levels are reduced in COVID-19) may assist in this sequestration process and contribute to hypoferremia." (PMID 35849261, 2023). "Serum hepcidin and ferritin/transferrin ratio can predict COVID-19 severity." (PMID 35849261, 2023). "TOSICA’s TF regulon attentions in C3 and C4 show that AP2_Q6 and FOXO4_01 have low activities and AP4_01, MIR3617_5P, NFKB_Q6, and ATF3_Q6 have upregulated activities during COVID-19 disease progression." (PMID 36641532, 2023). "Reported iron-related alterations in the sera of COVID-19 include decrements in iron, transferrin, transferrin saturation and hemoglobin (can show normal levels), and increments in ferritin, hepcidin (can be low), soluble transferrin receptor (in ICU patients) and lipocalin-2." (PMID 35849261, 2023). "Notably, in COVID-19 patients discharged from the hospital, transferrin levels were found to increase/normalize to 253 mg/dL (231–283 mg/dL) in around 122 days (median) after the discharge." (PMID 35849261, 2023). "It is shown that transferrin is a good marker for COVID-19 severity." (PMID 37790210, 2023). "Furthermore, TF abundance was discordantly downregulated in COV-NEG patients in comparison to HCO, suggestive of a COVID-19 causative specific increase in EBP." (PMID 36967377, 2023). "In contrast AAT and transferrin (TF) showed a sharp decline in COVID-19." (PMID 37031181, 2023). "Even though low serum transferrin has been observed at the time of COVID-19-related hospitalization, and the levels further decreased in those who died (associating decreasing transferrin levels with increasing severity), transferrin levels can vary during the hospital stay." (PMID 35849261, 2023). "Serum transferrin levels were low in COVID-19 outpatients and inpatients." (PMID 35849261, 2023). "Moreover, significant iron dysmetablolism with high serum ferritin and low serum iron and transferrin levels occurred, explaining disturbances of oxygen-binding capacity in severely ill COVID-19 patients." (PMID 35181867, 2022). "All these results suggest that the increased transferrin expression and transferrin/antithrombin ratio may heavily contribute to the development of COVID-19-related coagulopathy with more severe outcomes in older patients." (PMID 35682873, 2022). "In addition, our results corroborate that transferrin can be the missing link between COVID-19-related severe diseases." (PMID 35682873, 2022). "Furthermore, to more systematically understand the modulatory interaction of molecules of COVID-19-related CU, we constructed a key gene-TF-miRNA-lncRNA network." (PMID 36531995, 2022). "Subsequently, based on critical genes, the TF-gene networks and TF-miRNA coregulatory networks were studied for related pathway analysis to lay the foundation for further research and clinical diagnosis and treatment of COVID-19 Myocarditis." (PMID 35749386, 2022). "Increased ferritin and transferrin levels could indicate a strong inflammatory reaction in COVID-19 or is related to viral entry into the human body and its impact on iron metabolism." (PMID 34071293, 2021). "Interestingly, when we compared patients at the same level of disease severity, we found that COVID-19-positive patients always had significantly lower iron and transferrin levels than COVID-19-negative patients, except for serum iron in fatal cases." (PMID 34960751, 2021). "High expression of TF/CD142 on cells used in the treatment of COVID-19 could lead to dire consequences if the cells enhanced the already present pro-thrombotic effects of the viral infection itself." (PMID 33853637, 2021). "Our manual further investigations identified transferrin as a candidate factor, which may be involved in COVID-19-related coagulopathy." (PMID 32751741, 2020).
COVID-19 (continued). "Of concern, IV infusions of poorly characterized MSC products with unchecked (high) TF/CD142 expression could trigger blood clotting in COVID-19 and other vulnerable patient populations and further promote the risk for thromboembolism." (PMID 32574263, 2020). "Moreover, a rise of transferrin levels was observed in patients during COVID-19 disease progression." (PMID 32751741, 2020). "Therefore, because the change of transferrin is mainly regulated by the availability of iron, during the recovery phase of COVID-19 patients the levels of transferrin, especially TSAT, can be used as an important reference to guide the timing of iron supplementation." (PMID 39000113, 2024). "Thus, in COVID-19 patients, the transferrin isoform profiles differed compared to other clinical situations, which may be used for diagnostic purpose." (PMID 38673719, 2024). "However, in a different study, transferrin was significantly lower in mild cases compared to moderate and severe cases, and its levels positively were correlated with computed tomography scores that were indicative of COVID-19 severity." (PMID 35849261, 2023). "In the plasma of COVID-19 patients, the infection-related elevation of IL-6 and IL-6R results in a boost of endothelial cells and TF and this infection-induced coagulopathy may play a pivotal role in thrombocytopenia, while the cytokine storm triggers the thrombocytosis." (PMID 36295093, 2022). "However, the link between transferrin and COVID-19-related impairments is unclear." (PMID 35682873, 2022). "Moreover, the increased level of transferrin and the change in the transferrin/antithrombin ratio can lead to the dysfunction of the coagulation system, especially in males, which results in COVID-19-related hypercoagulopathy, thrombosis, and ischemic stroke." (PMID 35682873, 2022). "In addition, the levels of IL-5Rα, FABP2, CD200 and transferrin consistently showed the highest levels in the moderate group, indicating that these factors may serve as sensitive biomarkers reflecting COVID-19 disease severity." (PMID 34335566, 2021). "Hence, an increased transferrin/antithrombin ratio may contribute to COVID-19-related coagulopathy and more severe disease in older patients, in particular in males." (PMID 32751741, 2020). "We introduced a ferritin/transferrin ratio which seems to be a robust and easily available marker for risk stratification at initial presentation of patients in the hospital in terms of ICU admission and the need for mechanical ventilation in patients with COVID-19." (PMID 32751400, 2020). "Multiple small cohort studies in COVID-19 ICU patients also described low iron and transferrin levels at admission." (PMID 38337670, 2024). "The relationship of transferrin levels and TSAT with severity of disease was also reported in COVID-19 patients." (PMID 39000113, 2024). "Also, locally produced transferrin may aggravate COVID-19 pathology." (PMID 35849261, 2023). "Hence, there might be a link between transferrin levels and coagulation in COVID-19 patients." (PMID 32751741, 2020). "It is not yet clear if this is a safe and effective route of cell delivery in COVID-19, considering that MSC products express variable levels of highly procoagulant tissue factor (TF/CD142), compromising the cells' hemocompatibility and safety profile." (PMID 32574263, 2020). "In this study, we used mRNA-seq data from the peripheral blood of COVID-19 patients to identify six COVID-19 severe immune characteristic genes (FPR1, FCGR2A, TLR4, S100A12, CXCL1, and L TF), and found neutrophils to be the critical immune cells in COVID-19 severe disease." (PMID 38674681, 2024). "Ferritin, iron, and transferrin of patients with and without COVID-19 were similar (p > 0.05 for all)." (PMID 39200147, 2024).